TTC33 (tetratricopeptide repeat domain 33)
Synonyms: OSRF
Tractability: PROTAC: ubiquitination databases record sites on it.
Safety:
Unwanted effects reported when the protein is acted on. In parentheses: how it was acted on, where the effect was seen, and who reports it.
gastrointestinal toxicities (source: ClinPGx)
Gene: Protein-coding gene on chromosome 5 (40,512,333 to 40,755,963, reverse strand). Ensembl gene ENSG00000113638.
Subcellular location (Human Protein Atlas): Nucleoplasm; Golgi apparatus; Vesicles
Gene Ontology:
Molecular function: protein binding
Genetic constraint (gnomAD): Loss-of-function variants: 17 observed, 22.52 expected, observed/expected ratio (o/e) 0.76, 90% interval 0.52 to 1.13. The upper end of that interval is the gene's LOEUF score, 1.13, which puts it in group 4 of 6, group 1 being the genes least tolerant of losing a copy. Missense variants: 263 observed, 291.01 expected, observed/expected ratio (o/e) 0.9, 90% interval 0.82 to 1. Synonymous variants: 94 observed, 93.48 expected, observed/expected ratio (o/e) 1.01, 90% interval 0.85 to 1.19.
Homologues: Orthologues: chimpanzee TTC33 (99% identical), dog TTC33 (94% identical), rabbit TTC33 (94% identical), guinea pig TTC33 (91% identical), rat Ttc33 (83% identical), mouse Ttc33 (82% identical), pig TTC33 (59% identical), zebrafish ttc33 (53% identical), tropical clawed frog ttc33 (41% identical).
Diseases named in the same sentence as TTC33 in open-access papers:
TTC33 is named in the same sentence as 1 disease in open-access papers, as found by Europe PMC text mining. Sharing a sentence is not in itself a finding about the gene and the disease.
TTC33 shares sentences with these, for which no sentence is quoted: COVID-19 (1 paper).